MTOR (mechanistic target of rapamycin kinase)
Diseases named in the same sentence as MTOR in open-access papers (continued):
Sharing a sentence is not in itself a finding about the gene and the disease.
tumor (continued). "Once activated, Akt initiates downstream signaling cascades, including phosphorylation of mTOR and activation of NF-κB, thereby promoting tumor growth, enhancing chemoresistance, and inhibiting apoptosis." (PMID 40740310, 2025). "Honey has proven its potential role in tumor inhibition via the regulation or inhibition of the mTOR and AkT pathways." (PMID 40059876, 2025). "This process not only enhances the expression of cyclins (Cyclin D1/E) but also stimulates ribosomal biogenesis via activation of the mammalian target of rapamycin (mTOR) pathway, ultimately leading to a significant increase in tumor cell mitotic rates." (PMID 40568594, 2025). "mTOR inhibitors, particularly everolimus, have proven to be effective in controlling tumor growth and alleviating neurological and neuropsychiatric symptoms, offering considerable improvements in patient outcomes." (PMID 40141713, 2025). "This binding not only suppresses the enzymatic activity of JMJD2A but also interrupts the PDK1-Akt-mTOR signaling pathway, a vital cascade that is essential for tumor growth and survival." (PMID 41011214, 2025). "While the enrichment of ECM-related pathways is in line with the known roles of THBS2, FN1, COL1A1, and COL5A1 in extracellular matrix remodelling and tumour progression, the concurrent upregulation of mTOR signalling presents an intriguing finding." (PMID 40860666, 2025). "Tumor-induced hyperactivation of neuronal mTOR also affects the function of peritumoral inhibitory neurons, decreasing their firing rate and altering the timing of their firing with respect to excitatory neuron activity." (PMID 41301687, 2025). "The PI3K/AKT/mTOR signaling also influences immune interactions and promotes tumor progression within the TME." (PMID 40075635, 2025). "Though often overlooked, PD-L1 has several tumor intrinsic functions that have recently been identified to regulate mTOR/AKT, MAPK, STAT3/Caspase 7, integrin β4, MerTK, and BIM/BIK signaling, among others." (PMID 39663510, 2025). "Therapeutic strategies combining autophagy modulators or mTOR inhibitors with immunotherapy have been implemented in clinical trials targeting a variety of tumor types." (PMID 40900790, 2025). "To investigate the therapeutic mechanism of [177Lu]Lu-DOTA-CCK2R-dimer, we performed scRNA-seq analysis on tumor samples from AR42J tumor-bearing mice in the four experimental groups (Veh, mTOR, Lu, and Combo)." (PMID 40963930, 2025). "In this context, mTOR inhibitors, such as rapamycin, have demonstrated the induction of autophagy in tumor cells." (PMID 39863145, 2025). "For instance, glucose and oxygen consumption by tumor cells can limit T cell function, leading to reduced mTOR activity, diminished glycolytic capacity and impaired IFN-γ production." (PMID 40658684, 2025). "Trials evaluating the combined use of targeted therapies, such as PI3K/mTOR inhibitors with radiation, or immune checkpoint inhibitors alongside chemotherapy, seek to overcome resistance mechanisms and increase tumor vulnerability." (PMID 39796773, 2025). "In the context of this study, MYB is positioned as a key mediator in the miRNA-195-5p-regulated pathway, potentially linking it to the PI3K/AKT/mTOR signaling axis, which is critical for tumor growth and metabolism." (PMID 41141380, 2025). "In summary, CMTM4 prevents EGFR from lysosomal degradation, which further amplifies EGFR signaling and activation of the Akt/mTOR/NF-κB pathways to promote tumor growth." (PMID 39948411, 2025). "It has been reported to mediate multiple oncogenic signaling pathways, including the Wnt/β-catenin, MAPK, PI3K/AKT/mTOR, Notch, and Hedgehog pathways, thereby influencing tumor proliferation, invasion, and therapy resistance." (PMID 40759634, 2025). "In HCC models, sertraline enhanced therapeutic efficacy when combined with CDC7 inhibition by promoting apoptosis in senescent tumor cells through mTOR suppression." (PMID 40874450, 2025).
tumor (continued). "Asparagine aids in protein synthesis and restores mTOR activity, helping tumor cells proliferate and maintaining T-cell function." (PMID 41179661, 2025). "Leucine enhances mitochondrial biogenesis and activates mTOR signaling in skeletal muscle while simultaneously decreasing STAT3 phosphorylation and associated inflammatory signaling in tumor-bearing mice." (PMID 40704145, 2025). "Nevertheless, targeting signaling pathways activated in canine and human MM, such as Ras/MAPK and PI3K/AKT/mTOR, remain a viable option due to their frequent activation and vital role in supporting tumor growth." (PMID 40723239, 2025). "For example, TRIM25 down-regulates the activity of this protease through polyubiquitination modification of PTEN in non-small cell lung cancer, thus activating the PI3K/mTOR pathway to promote tumor development." (PMID 39759114, 2025). "Another important protein, LMP2A, promotes tumor cell immune escape through the PI3K/Akt/mTOR pathway, while inhibiting the expression of MHC class I molecules and reducing tumor cell immunogenicity." (PMID 40432090, 2025). "Dysregulation of the PI3K/AKT/mTOR pathway is a fundamental driver of oncogenesis and tumor advancement." (PMID 41008918, 2025). "Polymeric oligopeptide-modified pBAE nanoparticles, anisamide-functionalized for tumor selectivity, protect and deliver mTOR siRNA with serum stability, achieving specific NSCLC knockdown and antitumor efficacy in vitro and in vivo." (PMID 41304838, 2025). "Defects in LAL stimulate tumor growth through mTOR pathway regulation and activation of MDSCs, enabling immune evasion of metastatic tumor cells." (PMID 40698038, 2025). "As a downstream effector of this pathway, mTOR not only promotes protein synthesis and metabolic reprogramming but also enhances tumor cell tolerance and invasiveness by regulating HIF-1α." (PMID 40303931, 2025). "In contrast, miRNAs that were downregulated in rKGAS cells were shown to regulate tumor suppressor genes including IGF1R, TNFAIP3, and MTOR, suggesting a potential loss of tumor-suppressive signaling in rKGAS cells." (PMID 40952575, 2025). "It induces apoptosis and slows tumor cell proliferation by inhibiting the mammalian target of rapamycin (mTOR) signaling pathway." (PMID 40241724, 2025). "They reported that in vitro, DIAPH3 knockdown in HeLa and SiHa cells suppressed proliferation, colony formation, and tumor growth in mice, accompanied by mTOR pathway inactivation." (PMID 41148856, 2025). "The phosphatidylinositol 3-kinase (PI3K)/AKT/mammalian target of rapamycin (mTOR) signaling pathway is known to play an important role in tumor cell growth and proliferation in response to food availability, hormones, and growth factor stimulation." (PMID 40687439, 2025). "This complex is thought to interact with the 5⁣′ AMP-activated protein kinase, thereby acting as a negative regulator of the mTOR pathway and functioning as a tumor suppressor." (PMID 40740168, 2025). "Collectively, these data indicate that, while mTOR is a pivotal regulator of tumor metabolism, invasion, and angiogenesis in ARMS, inhibition of mTOR alone is insufficient due to compensatory activation of parallel signaling pathways." (PMID 40508013, 2025). "The expression of five protein proxies (CD31, GLUT1, phospho-mTOR S2448, Ki-67, H3K36me3) was analyzed in the tumor periphery and the tumor center of 15 primary tumors and two local recurrences." (PMID 40352587, 2025). "For instance, SDC1 overexpression in HCC suppresses autophagy via PI3K/AKT/mTOR activation, thereby enhancing tumor survival and metastatic potential." (PMID 41573680, 2025). "The convergence of medicarpin-associated targets within PI3K/AKT/mTOR, MAPK, and apoptosis-related signalling pathways highlights their ability to modulate critical oncogenic pathways that control tumour growth, survival, and treatment resistance in CCA." (PMID 41465766, 2025).
tumor (continued). "The hyperfunction of mTOR, such as the phosphorylation of mTOR at Ser2448, is the key factor that leads to the Warburg effect in tumor cells." (PMID 41219936, 2025). "The PI3K/AKT/mTOR pathway is typically hyperactivated in neoplastic cells, promoting tumor survival and proliferation." (PMID 40867215, 2025). "Another important axis of tumor metabolism is the mTOR-related and mitochondria-driven synthesis of purines, pyrimidines, and amino acids." (PMID 41469379, 2025). "ESM1 promotes angiogenesis and tumor progression in CRC through activation of the PI3K/Akt/mTOR signaling pathway and upregulation of pro-angiogenic and inflammatory factors such as VEGF, COX-2, and HIF-1α." (PMID 40722723, 2025). "mTOR signaling in both immune and tumor cells can modulate their response to chemerin and shape the overall tumor microenvironment 37,38." (PMID 40959100, 2025). "Liver transplantation is another option for selected patients, while TACE and mTOR inhibitors have also been used for tumor reduction prior to surgery." (PMID 40723161, 2025). "It was further shown that NPC tumor initiation is dependent on mTORC2 signaling, as the knockdown of Rictor or mTOR prevented NPC tumor formation." (PMID 40872852, 2025). "Other ubiquitination modifications can also exert a tumor growth-promoting role by enhancing the mTOR signaling pathway." (PMID 39759114, 2025). "More importantly, mTOR inhibition slows tumor proliferation, leading to suboptimal responses when combined with chemotherapy, as chemotherapy primarily targets rapidly dividing cells." (PMID 40299431, 2025). "SSF components have demonstrated strong anti-tumor and anti-metastatic activities by modulating apoptosis, tumor differentiation, activation of immune cells, and mTOR-related signaling." (PMID 40417000, 2025). "The PI3K/Akt/mTOR signaling pathway, which is upregulated in MM and central to tumor proliferation, is also known to activate hepatic stellate cells (HSCs) and promote hepatic fibrogenesis." (PMID 41458624, 2025). "Activation of the PI3K/AKT/mTOR pathway is a hallmark of NSCLC, correlating with poor prognosis, increased tumor aggressiveness, and resistance to various therapies." (PMID 39953539, 2025). "Studies have shown that the mTOR pathway promotes tumor proliferation and metabolism, and that asparagine can activate mTORC1 through Arf1." (PMID 40781327, 2025). "Many factors, including miMOMP, reactive oxygen species (ROS), epigenetic regulation, mammalian target of rapamycin (mTOR) and tumor suppressor pathways contribute to the induction of SASP and cellular senescence." (PMID 39944655, 2025). "Persistently activated PI3K/Akt/mTOR signalling in tumours reduces ubiquitination and degradation of Cyclin D, promotes synthesis and assembly of Cyclin D‐related proteins, and increases expression of the Cyclin D‐CDK4/6 complex." (PMID 40525649, 2025). "Its activating mutations (such as E542K, E545K, and H1047R) persistently activate the PI3K/Akt/mTOR signaling pathway, promoting tumor cell proliferation, survival, and metastasis." (PMID 40723456, 2025). "USP22 also regulates mTOR signaling, and its loss in CRC enhances mTOR activity and tumor burden, further underscoring the diverse context-dependent outcomes of DUB modulation." (PMID 41359051, 2025). "Recent studies have demonstrated that S100A10 interacts with annexin A2 (ANXA2) to activate the mTOR pathway, thereby promoting tumor glycolysis and driving malignant tumor progression." (PMID 41195005, 2025). "AKT phosphorylated by the PI3K complex tuberous sclerosis 1/2 (TSC1/2), initiates the AMPK pathway as a tumor suppressor by blocking mTOR activation." (PMID 40688079, 2025). "LHPP functions as a tumor suppressor gene in GC by regulating the PI3K/AKT/mTOR pathway and inhibiting the Wnt/β-catenin signaling pathway, the TGFβ/Smad signaling pathway, AKT phosphorylation, and other mechanisms to suppress tumor occurrence and progression." (PMID 40240758, 2025).
tumor (continued). "CuB achieves this by inhibiting the PI3K/Akt/mTOR pathway, which is crucial for tumor cell growth, proliferation, and survival." (PMID 39949780, 2025). "Targeting the PI3K/AKT/mTOR pathway is a promising strategy, as its dysregulation promotes tumor growth and survival." (PMID 40604062, 2025). "Suppressing ADCK2 profoundly inhibited NSCLC cell viability, proliferation, and motility, disrupted essential mitochondrial functions, and weakened Akt-mTOR signaling, ultimately curbing tumor growth." (PMID 41213905, 2025). "The VEGF pathway supports tumor growth through angiogenesis, and the mTOR pathway influences cell growth and metabolism." (PMID 40417653, 2025). "Catalytic mechanistic target of rapamycin (mTOR) inhibitors, which block both mTORC1 and mTORC2, often demonstrate stronger tumor cell killing but also higher toxicity and adverse effects." (PMID 41458042, 2025). "Numerous differentially expressed genes identified from both comparisons are linked to cell proliferation pathways such as PI3/AKT/mTOR and TNF-α, suggesting a tumor-prone or precancerous state in the mammary glands of tumor-bearing mice." (PMID 41387465, 2025). "Akt, a key component of the PI3K/Akt/mTOR pathway, can regulate tumor cell survival, proliferation, and metastasis." (PMID 41378083, 2025). "The expression levels of PI3K, Akt, and mTOR mRNA in mouse tumor tissues were measured using qRT‐PCR." (PMID 39648951, 2025). "The EGFR/PI3K/AKT/mTOR pathway is intricately involved in cell proliferation, survival, and tumor metastasis." (PMID 40699663, 2025). "HIF-1α regulates Glut-1 expression via the PI3K/AKT/mTOR pathway, facilitating glucose uptake and glycolytic metabolism in tumor cells to provide energy support." (PMID 40725100, 2025). "Recent advancements in research on natural compounds have provided evidence that certain natural medications can effectively hinder tumor progression by inhibiting mTOR signaling." (PMID 40949144, 2025). "The PI3K/AKT/mTOR pathway plays a critical role in tumor cell survival, proliferation, and immune evasion, often contributing to the creation of an immunosuppressive microenvironment that undermines the efficacy of PD-1 therapy." (PMID 39972480, 2025). "Targeted interventions, such as modulating RRM2, TS, and other key enzymes or disrupting the PI3K/AKT/mTOR pathway, have demonstrated potential in reducing tumor growth and inflammation in pancreatic tissue." (PMID 41200180, 2025). "Among these, the PI3K/AKT/mTOR pathway plays a crucial role in regulating tumor cell survival, proliferation, metabolism, and migration." (PMID 41259383, 2025). "Previous work has established that CQ induces AMPK activation through lysosomal stress, while the combinatorial use of AMPK activators with mTOR inhibitors has demonstrated synergistic tumor growth suppression with reduced mTOR inhibitor dosage." (PMID 40299634, 2025). "proved that metformin led to increased expression of AMPK and decreased expression of mTOR protein, thus inhibiting proliferation and increasing autophagy of tumor cells." (PMID 39944825, 2025). "RAS activation through AngII can enhance PI3K and mTOR activity, supporting tumor survival and metabolic adaptation." (PMID 41301459, 2025). "SOD1 serves as a downstream target of the mammalian target of rapamycin complex 1 (mTORC1), and mammalian target of rapamycin (mTOR) is thought to play a key role in promoting tumor cell survival and proliferation." (PMID 40867576, 2025). "Inhibition of VEGF has been shown to suppress TAM-driven tumor progression by targeting the AKT/mTOR axis, thereby reducing tumor cell proliferation, migration, and immune evasion." (PMID 40764998, 2025). "In vivo studies using xenograft models further validated the oncogenic role of PRR15, demonstrating that PRR15 knockdown suppressed tumor growth and attenuated Akt-mTOR activation." (PMID 39929816, 2025). "SNHG8 modulates autophagy and apoptosis via the AKT/AMPK/mTOR pathway, suppressing tumor progression." (PMID 41301542, 2025).
tumor (continued). "This review focuses on the role and molecular mechanisms of the PI3K/AKT/mTOR signaling pathway in tumor radioresistance, summarizes the progress in research on related inhibitors, and evaluates their potential applications in clinical radiotherapy." (PMID 40725100, 2025). "MTOR is the central hub regulator for tumor growth and can be abnormally activated by a variety of oncogenic factors or other epigenetic modifications." (PMID 40651979, 2025). "In this study, we found that HQF significantly induces apoptosis and inhibits tumor growth in HCC cells by suppressing the PI3K/AKT/mTOR pathway." (PMID 39972480, 2025). "The continual activation of the PI3K-Akt/mTOR pathway stimulates tumor proliferation and facilitates platinum-based chemoresistance by inhibiting apoptotic mechanisms and enhancing DNA repair." (PMID 41516052, 2025). "mTOR-axis genes partition into widely shared drivers versus tumor-specific nodes across histologies, testable via cross-tumor prevalence, entropy and τ-specificity metrics." (PMID 41300706, 2025). "FBXW7, as a critical tumor suppressor, targets various substrates for proteasome-mediated degradation of oncoproteins, including cyclin E, c-Myc, Mcl-1, mTOR, Jun, and Notch." (PMID 39747664, 2025). "LRP1 also drives tumorigenesis and tumor progression by activating AKT/mTOR signaling and inhibiting JNK and NF-κB pathways." (PMID 40625660, 2025). "Concurrently, PI3K/AKT/mTOR pathway hyperactivation promotes tumor metabolism and survival through enhanced glucose utilization and protein synthesis." (PMID 40510156, 2025). "The phosphatidylinositol 3-kinase/Akt/mammalian target of the rapamycin (PI3K/Akt/mTOR) pathway, governing cell survival and proliferation, can support tumor progression." (PMID 39857798, 2025). "The mTOR-selective inhibitor everolimus reduces tumor proliferation by irreversibly inhibiting the phosphorylation of S6K1." (PMID 40134916, 2025). "This intricate web means PI3K/AKT/mTOR dysfunction amplifies oncogenic signals across multiple pathways and undermines tumor suppressive mechanisms." (PMID 40740483, 2025). "RNA modifications affect tumor cell survival and death through various pathways, including the PD‐L1/PD‐1 and mTOR/AKT pathways." (PMID 39802639, 2025). "PTEN loss in GBM drives tumor progression and therapeutic resistance by dysregulating the PI3K/AKT/mTOR pathway, leading to uncontrolled cell growth, immune evasion, and an immunosuppressive TME." (PMID 40628732, 2025). "The central role of the mTOR pathway in cell growth and division makes it a potential target for anti-tumor drugs." (PMID 40969386, 2025). "DCA, a secondary BA produced by Clostridium sordellii, enhances EGFR activation and stimulates PI3K/AKT/mTOR signaling, leading to increased tumor cell proliferation, invasion, and angiogenesis through upregulation of VEGF mRNA." (PMID 40959527, 2025). "NDV causes oncolysis and activates the immune system, Everolimus hinders tumor cell proliferation by focusing on the mTOR pathway, and Beclin-1 regulates autophagy to enhance tumor cell death." (PMID 40403026, 2025). "Advanced techniques, such as immunofluorescence, TUNEL assay, and immunohistochemical labeling were employed to analyze the effects of APOC1 knockdown on the PI3K/AKT/mTOR signaling pathway and tumor formation in nude mice." (PMID 39873475, 2025). "The comparison of GSEA in MA-treated tumors to PT+MA-treated tumors demonstrated pathways suppressed by PT, and included important pathways central to tumor progression, including oxidative phosphorylation, glycolysis, hypoxia, and mTOR signaling." (PMID 40227411, 2025). "The results of GSVA enrichment analysis revealed that SH3D21 positive HCC cells exhibited enrichment in the different pathways associated with tumor proliferation, invasion, and immunosuppression, such as PI3K/AKT/mTOR, angiogenesis, EMT, IL6-JAK-STAT3." (PMID 40179068, 2025).